OLFM4 (olfactomedin 4)
Diseases named in the same sentence as OLFM4 in open-access papers (continued):
Sharing a sentence is not in itself a finding about the gene and the disease.
cancer (continued). "EPHB3 expression was higher in CRCs than in normal mucosa and was associated with the intestinal stem cell markers EPHB2, OLFM4, LRIG1, and a proposed cancer stem cell marker, CD44." (PMID 32294981, 2020). "For example, shifts in mitochondrial metabolism are well established for cancer cells and are accompanied by ectopic expression of olfactomedin 4 (OLFM4), a marker for actively cycling ISCs that also labels a subset of CRC cells." (PMID 33469536, 2020). "Induction of OLFM4 in cancer cells is an anti-apoptosis function and promotes proliferation of cancer cells." (PMID 29511474, 2017). "Much to our surprise, we found plasma levels of OLFM4 covering a wide range, but largely segregating both normals and cancer patients into two groups, one with OLFM4 levels that are barely detectable and one with levels that are 2–4 orders of magnitude higher." (PMID 26416558, 2015). "We examined expression of OLFM4 in epithelial cells by immunohistochemistry and found that OLFM4 is highly expressed in proliferating benign epithelial cells and in some carcinoma cells." (PMID 26416558, 2015). "In this scenario, prevention of apoptosis by upregulation of OLFM4 in early stages of malignancy would enable cancer cells to survive and proliferate." (PMID 25364714, 2014). "Although no causal link has been demonstrated between altered expression of olfactomedin proteins and cancer, correlations between expression of OLFM4 and cancer have been well documented." (PMID 25364714, 2014). "Olfactomedin 4 is expressed primarily in bone marrow cells, but also in prostate, small intestine, colon, and stomach, and is upregulated in cancers of the stomach, colon, breast, and lung." (PMID 22761659, 2012). "Interestingly, OLFM4 expression has been detected in a variety of cancers, including those of the colon, breast, lung, pancreas, stomach, prostate, colorectum, liver, ovary, and cervix." (PMID 39861713, 2025). "These CSCs interact with immunosuppressive immune cells thereby constructing immune‐suppressive niche, and inflammatory cancer‐associated fibroblast (iCAFs) to enhance stemness through upregulation of SOX9 and OLFM4, promoting drug resistance and proliferation via the AREG‐ERBB2 signaling pathway." (PMID 39950944, 2025). "Through comprehensive bioinformatic analysis including volcano plots, heatmaps of the top 100 DEGs, and Venn diagram analysis of the top 100 DEGs and cancer-related (DO-enriched) and mitochondrial (GO-enriched) genes, OLFM4 emerged as a prime candidate for functional investigation." (PMID 40422535, 2025). "OLFM4 has been proposed to function as an “inducible resistance factor” against apoptotic triggers such as radiation and chemotherapy, highlighting its potential as a therapeutic target in cancer treatment." (PMID 39861713, 2025). "Additionally, the underexpression of Olfactomedin-4 (OLFM4), Ectonucleotide Pyrophosphatase/Phosphodiesterase (ENPP), or nucleic acid-associated proteins was observed to increase the cancer risk in these patients." (PMID 40507799, 2025). "Although these pathways are associated with bacterial infection, gastrointestinal inflammation, and cancer, they suggest that OLFM4 may be protective of PTB as it relates to cervical epithelium." (PMID 40429621, 2025). "Olfm4 is a secreted glycoprotein that has a regulatory role for cell proliferation and apoptosis implicating the gene in innate immunity, inflammation, and cancer." (PMID 36758370, 2023). "Generally, OLFM4 promotes S-phase transition in cancer cell proliferation." (PMID 36966136, 2023). "Although OLFM2 is involved in the regulation of the energy metabolism and OLFM4 is an important player in inflammation, innate immunity and cancer, the role of OLFMs in NAFLD-related intestinal dysbiosis remains unknown." (PMID 35806447, 2022).
cancer (continued). "The strongest association signal for PTSD was found on chromosome 13 (P = 4.79 × 10–20), in a region spanning noncoding mRNAs LINC01065, PCDH8P1, and RN7SL618P as well as olfactomedin 4–encoding gene OLFM4, which takes part in innate immunity, inflammation, and cancer." (PMID 33905376, 2022). "The observed expansion of OLFM4+ and POU5F1+ transient amplifying cells may contribute to disease progression and increased cancer risk." (PMID 33570127, 2021). "Higher expression of OLFM4, a cancer stemness gene induced by IL-22, is present in PSC-UC, suggesting that IL-22 responses may result in alterations of the intestinal stem-cell niche in these patients." (PMID 33570127, 2021). "Mll1 also controls the intestinal stem cell genes Smoc2, Igfbp4, and Olfm4, which are induced in Wnt-mutated cancer cells but regulated by other signaling pathways such as Notch and NF-κB52,53." (PMID 33349639, 2020). "Aberrant expression of OLFM4 has been shown in several cancers." (PMID 26416558, 2015). "Instead, we observed two populations of individuals with respect to OLFM4 levels in plasma, the majority with OLFM4 in plasma between 0 and 0.1 μg/ml, mean 0.028 μg/ml while 10% of both normals and patients with cancers had OLFM4 between 4 and 60 μg/ml, mean 15 μg/ml." (PMID 26416558, 2015). "OLFM4 was identified as a gene highly up‐regulated in cancers of the gastrointestinal tract." (PMID 26416558, 2015). "Furthermore, OLFM4 is an important player in the cellular process of inflammation, and it has important roles in innate immunity against bacterial infection, gastrointestinal inflammation, and cancer." (PMID 35806447, 2022). "Therefore, OLFM4 might be a potential noninvasive biomarker for several cancer types, including HCC." (PMID 34912753, 2021). "To date, the antiapoptotic genes OLFM4, SIRT1, PIM-1, and DOCK3, the tumor suppressor PTEN, the cell proliferation and invasion genes CITRON and CLDN10, and FGF9 expressed by cancer-associated fibroblasts have been reported as potential targets for miR-486/miR-486-5p in malignant disease." (PMID 26895105, 2016). "However, the biological effects of OLFM4 differ between the types of cancer." (PMID 25797252, 2015). "In particular, targeting OLFM4+ CSCs through the synergistic use of DC vaccines and M-HIFU represents a critical step toward personalized and precise cancer immunotherapy." (PMID 39861713, 2025). "OLFM4, Histone H3, HTT activate HSPA5, an important molecule that tends to lead to cancer metastasis." (PMID 38304289, 2023). "We then performed qPCR analysis using total RNA isolated from the GFP- and RFP-enriched cells for cancer stem cell markers, LGR5, CD133, CD166, and OLFM4." (PMID 33946505, 2021). "In the present study, we first measured OLFM4 level in HCC patients and healthy controls and mRNA expression level in liver paracancerous and cancer tissues." (PMID 34912753, 2021). "Changes in the expression of SECTM1 and OLFM4, as well as in the activity of TGR5, play a role in the immunological tolerance to cancer cells and the colonization of tissues by bacteria." (PMID 30944407, 2019). "miR-486 has been shown to participant in general tumorigenesis by targeting the anti-apoptotic OLFM4, SIRT1, PIM-1 and protumorigenic ARHGAP5 in various types of cancer." (PMID 27167342, 2016). "In the human intestine, OLFM4 was identified as a robust marker of LGR5+ stem cells and a subset of cancer cells." (PMID 26561938, 2015). "It has been reported that OLFM4 possesses anti-apoptotic properties counteracting H2O2- or other cytotoxic agent-induced apoptosis and promotes proliferation of cancer cells." (PMID 24495253, 2014). "Low expression of cancer-related genes, such as NANOG, and high expression of infection-related genes, such as OLFM4, could be predictive markers for the efficacy of eradication therapy." (PMID 36831547, 2023).
cancer (continued). "A feature plot of Olfm4 in the spatial transcriptomics uterine tissue sections showed high expression in cancer regions in the DES sample and a lack of expression in the CO." (PMID 37856394, 2023). "Olfactomedin-4 (OLFM4) is an olfactomedin-domain-containing glycoprotein, which regulates cell adhesion, proliferation, gastrointestinal inflammation, innate immunity and cancer metastasis." (PMID 35218417, 2022). "miR-34a inhibits cancer stemness via targeting CD44; miR-34a expression inhibits TGF-β-induced EMT and downregulates Snail, Slug and ZEB1 as well as the stemness factors (BMI1, CD44, CD133, OLFM4 and c-MYC)." (PMID 30885232, 2019). "Olfactomedin 4 expression was highly up-regulated in more differentiated cancers and remarkably reduced or absent in poorly differentiated or undifferentiated cancers." (PMID 24495253, 2014). "Therefore, the correlation between OLFM4 expression and cancer prognosis is controversial and has not yet been confirmed." (PMID 31923206, 2020). "Thus, we postulate that OLFM4 expression is not essential for cancer cell survival, which is in accordance with a recent observation that genetic knock-out mice for OLFM4 show normal development and hematopoietic phenotypes." (PMID 22471589, 2012). "We cannot, of course, rule out that cells in the GI tract are the source of plasma OLFM4, but find this highly unlikely as we find a uniform staining of cells among the sections examined and also find that plasma levels do not correlate with the presence or absence of cancers in the GI tract." (PMID 26416558, 2015). "DES-exposed wild-type mice had high levels of OLFM4, but neither controls nor either of the DES-exposed cKO lines expressed this cancer marker." (PMID 37856394, 2023). "Immunofluorescent staining of primary CRC sections with antibodies directed against the stem cell marker OLFM4, the proliferation marker KI67, and the differentiation markers TFF3 and FABP1 revealed cell heterogeneity, but not how cancer cells in the tissue are related to each other (Fig EV4)." (PMID 34409732, 2021).
infection (27 papers, 2011 to 2026). The state of being infected such as from the introduction of a foreign agent such as serum, vaccine, antigenic substance or organism. "We identified decreased expression of CD64 (a marker associated with response to infection), in OLFM4+ neutrophils." (PMID 32470072, 2020). "OLFM4 is an important regulator of apoptosis and at a peripheral level it can be a marker of infection." (PMID 40063315, 2025). "Increased mRNA level of OLFM4 during peak infection, particularly in EM + CP treatment, is likely related to the promotion of intestinal epithelial cell regeneration in response to the increased intestinal inflammation." (PMID 39759108, 2024). "This population includes several neutrophil-associated genes (OLFM4, CD177, SERPINB1, S100P, PTX3 and MMP8), suggesting that there is an accumulation of neutrophils in PBCMs during the course of infection." (PMID 27595844, 2016). "The genes used (matrix metallopeptidase 9, olfactomedin 4, NB1 glycoprotein and lipocalin 2) were previously identified as predictive for severity of disease caused by infection with respiratory syncytial virus (RSV)." (PMID 26298058, 2015). "Although we cannot draw a strong comparison with the eel model, as herein we studied two phylogenetically distinct hosts, implication of OLFM4 in regulation of inflammation during the infection with an evolutionary-established parasite deserves further research." (PMID 36590595, 2022). "We were, however, unable to identify if the increased OLFM4 was because those patients always expressed high levels of OLFM4, or if high expression was induced by infection and organ injury because we only collected samples at the time of admission when patients were already critically ill." (PMID 32470072, 2020). "We did not detect an association between percentage of OLFM4+ neutrophils and infection (positive blood culture)." (PMID 32470072, 2020). "Finally, given the immune suppression and increased susceptibility to serious infections, as well as other morbidities like GVHD and thrombotic microangiopathy (TMA), we sought to correlate these clinical events with changes in OLFM4 expression." (PMID 32470072, 2020). "By immunofluorescence analysis of littermate mice, we also found that Olfm4+ crypt base columnar (CBC) stem cells are greatly reduced in both Il-22−/− and Il-18−/− crypts at the steady state or during AIEC infection 26,35." (PMID 35169117, 2022). "We found that induction of HES1 and OLFM4 and the down-regulation of ATOH1 transcript levels was consistent with the increased Notch-1 signalling in crypts at the peak of infection." (PMID 28323899, 2017). "Remarkably, olfactomedin 4 (OLFM4) demonstrates a binary expression pattern within neutrophils either expressing high amounts of OLFM4 or none during both health and active infection." (PMID 32470072, 2020). "It is known that OLFM4 is upregulated during, and plays a role in, tumorigenesis, and mouse studies have indicated a negative role of OLFM4 during infection." (PMID 23922742, 2013).
bacterial infections (15 papers, 2013 to 2025). "Genes regulating major histocompatibility complex (MHC) molecules and pathogenic bacterial infections were enriched in OLFM4+ epithelial cells and colonocytes." (PMID 38889269, 2024). "It was previously shown that OLFM4 can negatively regulate the defense response against bacterial infections." (PMID 36579331, 2022). "The only protein-coding gene in this region, olfactomedin 4 (OLFM4), is associated with down-regulation of immune responses against bacterial infections in mice." (PMID 31697674, 2019). "Nevertheless, OLFM4 also plays an important role in innate immunity against bacterial infection, regulates gastrointestinal inflammation and is a promising biomarker for certain viral and bacterial infections." (PMID 36506087, 2022). "Other components are olfactomedin-4 (OLFM-4), which helps fight bacterial infections such as Staphylococcus aureus, resistin, a pro-inflammatory cytokine and T-cell chemoattractant, the receptor CD177 and antimicrobial neutrophil gelatinase-associated protein lipocalin (NGAL)." (PMID 33936029, 2021). "Smaller portions of neutrophils express olfactomedin-4 (OLFM-4), which may regulate the inflammatory reaction to bacterial infections or evoke ANCA vasculitis." (PMID 38189129, 2024). "OLFM4 expression in human neutrophils was upregulated in response to a wide range of bacterial infections, including Gram-positive S. aureus, Gram-negative E. coli and S. enterica infections." (PMID 36035204, 2022). "In chronic granulomatous patients, deletion of OLFM4 enhances resistance to bacterial infection through non-oxidative mechanisms." (PMID 36451813, 2022). "In summary, OLFM4 was upregulated in several viral and bacterial infections in many (but not all) previously published studies investigated." (PMID 26162090, 2015). "Although it has not been investigated whether OLFM4-defined subpopulations are present in mice, our data agree with murine studies comparing OLFM4 knockout with wild type mice that argue for a negative role of OLFM4 during bacterial infection, despite similar levels of neutrophil phagocytosis." (PMID 23922742, 2013).
adenocarcinoma (8 papers, 2012 to 2023). A common cancer characterized by the presence of malignant glandular cells. "OLFM4 expression was found to be frequently diminished in SBA, with targeted OLFM4-RET expression leading to development of adenocarcinoma in mouse models." (PMID 35267592, 2022). "For this, two specimens of adenocarcinomas arising in the background of BE were assessed for the expression of CDX2, OLFM4, EPHB2, and PROM1 by qRT-PCR analysis." (PMID 25996368, 2015).
infectious disease (4 papers, 2015 to 2023). A disorder directly resulting from the presence and activity of a microbial, viral, or parasitic agent in humans. "As a neutrophil granule-specific protein expressed in circulating mature neutrophils, OLFM4 has clinical value as a potential biomarker and intervention target for infectious diseases." (PMID 36451813, 2022). "To validate the OLFM4 gene expression changes during infectious disease we data-mined other micro-array studies that described pediatric and adult patient cohorts." (PMID 26162090, 2015). "Interestingly, compared with OLFM4+ neutrophils, OLFM4- cells produce distinct NETs in vitro and may be effective than positive neutrophils in infectious diseases." (PMID 36674682, 2023). "To date, no reports have suggested that OLFM4 affects mood and behavior by regulating neuroinflammation and neurodevelopment, but it was reported to contribute to the severity of infectious disease." (PMID 37280213, 2023).
digestive diseases (3 papers, 2022 to 2024). "Likewise, OLFM4 is a highly specific marker reported in murine and human intestinal stem cells and its expression is regulated by the NF-κB, Notch, and Wnt signaling pathways in digestive diseases." (PMID 35884586, 2022).
gastrointestinal tumors (2 papers, 2014 to 2020). "Expression of OLFM4 by stem cells within the crypts of the intestinal mucosa has also led to the evaluation of plasma OLFM4 for prognostic potential in gastrointestinal tumors." (PMID 32470072, 2020).
gynecological tumors (2 papers, 2014 to 2016). "Elucidation of the effect of OLFM4 on gynecological tumour and its association with ER signalling is of great importance." (PMID 24495253, 2014). "We previously demonstrated that aberrant OLFM4 expression also occurs in gynecological tumors." (PMID 26871282, 2016).
metabolic disorders (2 papers, 2022 to 2025). "For example, OLFM4 expression was downregulated in LPS-induced lung epithelial cells, and it exhibited anti-inflammatory activity through modulating metabolic disorders." (PMID 36035204, 2022).
gastrointestinal disease (1 paper, 2022). A disease that occurs in the gastrointestinal system, excluding the hepatobiliary system. "The proteins olfactomedin 4 (OLFM4) and lysozyme (LYZ) are part of the intestinal mucosal defense and especially OLFM4 has rarely been evaluated in neonatal gastrointestinal diseases." (PMID 35410162, 2022).
prostate (1 paper, 2020). "Therefore, our identification of multiple OLFM4-expressing stem/progenitor-like cells may contribute to the identification of the cell types of origin in prostatic diseases." (PMID 33318499, 2020). "In particular, OLFM4 most frequently co-expressed with LY6D, a marker for prostate stem cells that are castration resistant and an origin for prostate cancer." (PMID 33318499, 2020).
skin disorder (1 paper, 2022). Any deviation from the normal structure or function of the skin or subcutaneous tissue that is manifested by a characteristic set of symptoms and signs. "As the histological analysis of recovering human and mouse wounds indicated that OLFM4 was induced at the proliferative phase of wound healing, we next sought to investigate whether its expression pattern was altered in skin disorders." (PMID 35218417, 2022).
OLFM4 also shares sentences with these, for which no sentence is quoted: COVID-19 (5 papers); gastric tumor (4); influenza (3); papillary thyroid carcinoma (2); Primary Sclerosing Cholangitis (2); acute lung injury (1); autoimmune gastritis (1); benign prostatic hyperplasia (1); bile reflux (1); Brain atrophy (1); cardiovascular disease (1); chronic gastritis (1); co-infection (1); cognitive decline (1); colorectal polyp (1); Cryptococcal meningitis (1); cystitis (1); gallbladder cancer (1); gastritis (1); gynecological cancers (1); hypertensive (1); immune diseases (1); inflammation (1); intestinal disorder (1); invasive breast carcinoma (1); ischemia (1); lung disease (1); lymphoepithelioma (1); metabolic syndrome (1); myxoid liposarcoma (1).
A further 17 diseases each share a sentence with OLFM4 in 1 paper.